Y_RNA (Y RNA )
Gene: Miscellaneous RNA gene on chromosome 4 (55,412,636 to 55,412,738, forward strand). Ensembl gene ENSG00000239040.
Homologues: Orthologues: macaque Y_RNA (95% identical). Paralogues in human: Y_RNA (86% identical), Y_RNA (85% identical), RNY3 (84% identical), Y_RNA (84% identical), RNY3P1 (83% identical), RNY3P9 (83% identical), Y_RNA (83% identical), Y_RNA (82% identical), RNY3P2 (81% identical), Y_RNA (81% identical), RNY3P11 (80% identical), RNY3P16 (80% identical), and 94 more.